STX16-NPEPL1 (STX16-NPEPL1 readthrough (NMD candidate))
Gene: Protein-coding gene on chromosome 20 (58,651,434 to 58,715,410, forward strand). Ensembl gene ENSG00000254995.
Genetic constraint (gnomAD): Missense variants: 295 observed, 359.62 expected, observed/expected ratio (o/e) 0.82, 90% interval 0.75 to 0.9. Synonymous variants: 127 observed, 134.77 expected, observed/expected ratio (o/e) 0.94, 90% interval 0.81 to 1.09.